RNU1-42P (RNA, U1 small nuclear 42, pseudogene)
Gene: Small nuclear RNA gene on chromosome 17 (48,949,361 to 48,949,520, reverse strand). Ensembl gene ENSG00000200903.
Homologues: Orthologues: chimpanzee U1 (99% identical), macaque U1 (89% identical), pig U1 (78% identical), rat LOC120094916 (78% identical), rabbit U1 (66% identical), mouse Gm22810 (64% identical), rat U1 (64% identical), guinea pig U1 (63% identical), rabbit U1 (62% identical), mouse Gm54374 (57% identical). Paralogues in human: RNU1-1 (89% identical), RNU1-2 (89% identical), RNU1-27P (89% identical), RNU1-28P (89% identical), RNU1-3 (89% identical), RNU1-4 (89% identical), RNVU1-18 (89% identical), RNVU1-29 (89% identical), U1 (89% identical), RNVU1-28 (89% identical), RNVU1-7 (89% identical), RNVU1-31 (88% identical), and 134 more.